ITM2C (integral membrane protein 2C)
Description:
Negative regulator of amyloid-beta peptide production. May inhibit the processing of APP by blocking its access to alpha- and beta-secretase. Binding to the beta-secretase-cleaved APP C-terminal fragment is negligible, suggesting that ITM2C is a poor gamma-secretase cleavage inhibitor. May play a role in TNF-induced cell death and neuronal differentiation (By similarity).
Synonyms: BRI3; E25; hRPC.1050_D_4; ITM3; BRICD2C; E25C
Tractability: Antibody: UniProt places it where antibodies can reach, with high confidence; its Gene Ontology location is reachable by antibodies, with high confidence; UniProt predicts a signal peptide or a membrane-spanning region. PROTAC: ubiquitination databases record sites on it; its protein half-life has been measured.
Gene: Protein-coding gene on chromosome 2 (230,864,639 to 230,879,248, forward strand). Ensembl gene ENSG00000135916.
Subcellular location: Lysosome membrane; Cell membrane
Gene Ontology:
Molecular function: amyloid-beta binding; protein binding; ATP binding
Biological process: negative regulation of neuron projection development; neuron differentiation; negative regulation of amyloid precursor protein biosynthetic process; positive regulation of extrinsic apoptotic signaling pathway
Cellular component: extracellular exosome; Golgi apparatus; lysosome; perinuclear region of cytoplasm; plasma membrane; lysosomal membrane
Genetic constraint (gnomAD): Loss-of-function variants: 16 observed, 20.85 expected, observed/expected ratio (o/e) 0.77, 90% interval 0.52 to 1.17. The upper end of that interval is the gene's LOEUF score, 1.17, which puts it in group 5 of 6, group 1 being the genes least tolerant of losing a copy. Missense variants: 332 observed, 334.62 expected, observed/expected ratio (o/e) 0.99, 90% interval 0.91 to 1.09. Synonymous variants: 158 observed, 145.14 expected, observed/expected ratio (o/e) 1.09, 90% interval 0.96 to 1.24.
Homologues: Orthologues: chimpanzee ITM2C (100% identical), macaque ITM2C (99% identical), mouse Itm2c (93% identical), rat Itm2c (93% identical), guinea pig ITM2C (90% identical), pig ITM2C (88% identical), dog ITM2C (63% identical), zebrafish itm2ca (58% identical), zebrafish itm2cb (57% identical), Caenorhabditis elegans itm-2 (24% identical), Drosophila melanogaster CG3662 (23% identical). Paralogues in human: ITM2B (43% identical), ITM2A (36% identical).
Diseases named in the same sentence as ITM2C in open-access papers:
ITM2C is named in the same sentence as 13 diseases in open-access papers, as found by Europe PMC text mining. Sharing a sentence is not in itself a finding about the gene and the disease. The quoted sentences say what the papers report.
Alzheimer disease (3 papers, 2021 to 2024). A progressive, neurodegenerative disease characterized by loss of function and death of nerve cells in several areas of the brain leading to loss of cognitive function such as memory and language. "ITM2C expression is associated with synapse formation and decreased GABAergic transmission, while its disruption has been linked to Alzheimer’s disease." (PMID 33562186, 2021). "Together, Itm2b, Itm2c, Cst3 and Clu potentially ameliorate Alzheimer’s disease." (PMID 38017352, 2024).
colorectal cancer (3 papers, 2023 to 2025). A primary or metastatic malignant neoplasm that affects the colon or rectum. "The mouse homolog Itm2c, an integral transmembrane protein, has been reported to function in the brain, and recently human ITM2C has been associated with colorectal cancer." (PMID 40495676, 2025). "Integral membrane protein 2C (ITM2C), a member of the ITM protein family, is considered a tumor suppressor gene in colorectal cancer and may inhibit tumor cell growth and division." (PMID 38531846, 2024).
asthma (2 papers, 2022 to 2025). "ITM2C, TXNDC5, and TXNDC11, though less studied in asthma, are involved in the endoplasmic reticulum secretory machinery of plasma cells, coordinating protein folding, quality control, and trafficking to support high-rate antibody synthesis and secretion." (PMID 40950420, 2025).
dissection (2 papers, 2021 to 2022). The separation and isolation of tissues for surgical purposes, or for the analysis or study of their structures. "A study conducted on surgical samples of arterial wall form patients with acute aortic dissections, showed that ITM2C, an integral membrane protein, was under-expressed while miR-107-5p complex was over-expressed." (PMID 37476203, 2022).
multiple myeloma (2 papers, 2018 to 2024). "The expression of PLPP5, CLPTM1L and ITM2C varied between different established human myeloma cell lines, however, all cell lines examined had detectable expression of at least one of these genes of interest." (PMID 30042348, 2018).
adenoma (1 paper, 2023). A neoplasm arising from the epithelium. "The genes CA2, CA7, and ITM2C collectively play critical roles in CRC progression, with CA2 influencing adenoma characteristics and cell proliferation, CA7 acting as a tumor suppressor gene, and ITM2C likely sharing similar tumor-suppressive properties with its family member ITM2A." (PMID 37895185, 2023).
colon cancer (1 paper, 2023). "ITM2C expression exhibited a strong correlation with the Act_B (rho = 0.146, p = 0.00172) and Neutrophils (rho = 0.126, p = 0.00692) levels in colon cancer and with the Act_B (rho = 0.329, p = 1.58 × 10−5) and Neutrophils (rho = 0.27, p = 0.000433) levels in rectal cancer." (PMID 37895185, 2023).
tumor (4 papers, 2019 to 2025). "In contrast, VDAC3-CAF-C1 and ITM2C-CAF-C5 were significantly enriched in pathways associated with tumor-related inflammatory responses." (PMID 40145099, 2025). "Though ITM2C was identified with high expression level in HCV-induced HCC tissues compared to HCV-induced HCC non-tumor liver tissues, we found only a very mild increase of ITM2C induced by HCV replication in Huh-7.5 cells." (PMID 31200545, 2019).
cancer (3 papers, 2018 to 2023). A tumor composed of atypical neoplastic, often pleomorphic cells that invade other tissues. "Genes such as PYGM, BMF, MBNL3, DENND6A, REEP5, KLF6 and ITM2C are potentially regulated by circYPEL2 and involved in cancer-specific pathways, which are needed to be validated in further studies." (PMID 35052380, 2021). "PLPP5, CLPTM1L and ITM2C are poorly characterized proteins, whose functions are unknown, although mutation in CLPTM1L has been associated with several human cancers (see Discussion)." (PMID 30042348, 2018). "Further analysis of an external CRC dataset and various literature sources revealed that CA2, CA7, and ITM2C could act as gene signatures for the early detection of CRC and showed the potential to regulate cell growth and division in a manner that could prevent cancer progression." (PMID 37895185, 2023).
infection (2 papers, 2013 to 2020). The state of being infected such as from the introduction of a foreign agent such as serum, vaccine, antigenic substance or organism. "Surprisingly, despite the widespread infection with the virus, changes in the transcriptome remained limited to only a few genes: GALR3, EGR1, E2F2, RNY4, DBX2 were found upregulated, and ITM2C was downregulated." (PMID 33490061, 2020).
ITM2C also shares sentences with these, for which no sentence is quoted: Allergy (1 paper); breast carcinoma (1); rectal cancer (1).